IL22 (interleukin 22)
Diseases named in the same sentence as IL22 in open-access papers (continued):
Sharing a sentence is not in itself a finding about the gene and the disease.
vaginal candidiasis (7 papers, 2013 to 2026). "During vulvovaginal candidiasis, IL-22-deficient mice also showed pronounced neutrophil recruitment to the vaginal epithelium, followed by increased production of AMPs, such as S100A8 and S100A9, as well as elevated tissue damage." (PMID 32517114, 2020). "The same trend was also evident in the vaginal candidiasis-associated inflammatory cytokines, IL-17, IL-22, and TNF-α." (PMID 31333606, 2019). "Thus, confirming recent findings, the neutrophil response in vaginal candidiasis occurs independently of IL-22 and IL-17F." (PMID 23853597, 2013).
viral hepatitis (7 papers, 2012 to 2025). An acute or chronic inflammation of the liver parenchyma caused by viruses. "A recent report demonstrates that IL-22 is produced locally in livers of patients with chronic viral hepatitis." (PMID 22967278, 2012). "However, IL-22 alone can protect hepatocytes from apoptosis in viral hepatitis-induced liver damage." (PMID 37403036, 2023). "Dambacher and colleagues supported our findings by showing that individuals with viral hepatitis did not have significantly different IL-22 serum levels compared to healthy individuals." (PMID 38273234, 2024).
Achalasia (6 papers, 2015 to 2025). A disorder of esophageal motility characterized by the inability of the lower esophageal sphincter to relax during swallowing and by inadequate or lacking peristalsis in the lower half of the body of the esophagus. "A review of the literature suggests that TNF-α, IL-6, IFN-γ, IL-12, IL-17, IL-22, and IL-23 theoretically could contribute to the underlying etiology of achalasia." (PMID 30744559, 2019). "This method allowed us to identify how white blood cell subpopulations (Th1, Th2, Th17, Tregs, Bregs and pDCregs) and cytokines (IL-22) relate to achalasia." (PMID 38267468, 2024). "Another study compared the plasma immunological profiles of TNF-α, IL-6, IFN-γ, IL-12, IL-17, IL-22 and IL-23 in 53 patients with achalasia, 22 eosinophilic esophagitis (EoE), and 20 gastroesophageal reflux disease, through Quantikine Human Immunoassays." (PMID 39337632, 2024). "It was found that the levels of IL-17 and IL-22 were significantly increased in the 14 patients who were diagnosed with achalasia compared with those in 14 healthy individuals." (PMID 34631047, 2021). "The primary aim of our study was to compare the differences in plasma immunological profiles (TNF- α receptor, IL-6, IFN-γ, IL-12, IL-17, IL-22, and IL-23) of patients with achalasia, eosinophilic esophagitis (EoE), and gastroesophageal reflux disease (GERD)." (PMID 30744559, 2019). "IL-17 and IL-22 concentrations in myenteric plexus esophageal tissue of achalasia patients are higher versus control." (PMID 30744559, 2019). "The primary aim of our study was to compare the plasma immunological profiles of plasma of TNF-α, IL-6, IFN-γ, IL-12, IL-17, IL-22, and IL-23 in patients with achalasia, EoE, and GERD." (PMID 30744559, 2019). "IL-17A-and IL-22-producing cells were the main cellular components of the inflammatory foci in achalasia tissue." (PMID 26078981, 2015). "In this study, we investigated plasma biomarker levels of IL-6, IL-12p70, IL-17, IL-22, IL-23, TNFα and INF-γ in patients with achalasia, EoE, and GERD." (PMID 30744559, 2019). "In the sera of patients with achalasia, we observed increased levels of IFN-γ, IL-17, and IL-22 compared with HD, suggesting that this systemic inflammation could contribute to the increase in RDW." (PMID 41323008, 2025). "However, IL-22+ cell number was increased in type II and type III achalasia versus type I achalasia." (PMID 26078981, 2015).
acute GVHD (6 papers, 2016 to 2025). "Given the IL-22 properties in these tissues, several groups assessed IL-22 contribution in acute GVHD models." (PMID 27148267, 2016). "This particularity should be kept in mind when IL-22−/− mice are used as recipients in gastrointestinal acute GVHD models." (PMID 27148267, 2016). "In preclinical models of acute GVHD, treatment with recombinant IL-22 has been shown to alleviate disease symptoms, increase the population of Lgr5+ stem cells, upregulate the expression of antimicrobial peptides such as Reg3α and Reg3γ, and improve epithelial integrity." (PMID 40943537, 2025). "Consistent with this approach, a recent phase II clinical trial provides evidence that combining IL-22 administration with systemic steroids may lead to improved treatment responses in patients with newly diagnosed lower-GI acute GVHD." (PMID 38349762, 2024). "It is also reported that IL-22 aggravates murine acute graft-versus-host disease by expanding effector T cells and reducing Treg cells though the underlying mechanisms remain unclear." (PMID 29383167, 2017).
adenoma (6 papers, 2019 to 2024). A neoplasm arising from the epithelium. "Though effector Th response increased during the carcinoma process, the ILC-derived IL-22 production was downregulated in the HP, adenoma, and CRC groups." (PMID 38343544, 2024). "The similarity in the tissue pathology during hyperplasia (4–6 weeks) and adenoma/MIN (6–8 weeks) between IL‐22+/+ and IL‐22−/−/PyMT mice was also confirmed by Ki‐67 cell proliferation marker staining." (PMID 31725949, 2020). "We measured IL‐22 protein levels in primary tumors from the initiation, hyperplasia, adenoma, early carcinoma, and late carcinoma stages." (PMID 31725949, 2020). "This stress response correlated with enhanced DNA damage, which in turn correlated with the accelerated transformation of ApcMin/+ cells to ApcMin/Min genotype in the presence of IL-22, which ultimately leads to development of adenomas." (PMID 31770366, 2019). "The mammary glands from these mice were harvested at 6 (hyperplasia) and 8 (adenoma/MIN) weeks of age and examined for any enhancement in these stages due to elevated levels of IL‐22 in the system." (PMID 31725949, 2020).
cerebral malaria (6 papers, 2016 to 2022). A sequestration of Plasmodium falciparum in the brain, which can cause coma and/or seizures. "Among these reports, it was discovered that polymorphisms in IL-22 were equally associated with a predisposition for childhood cerebral malaria." (PMID 33851257, 2021). "These functional data and our genetic results suggest that the IL22 SNPs, rs2227476 and rs2227473 may be causal for cerebral malaria." (PMID 28139719, 2017). "In 2017, another recent study on infectious disease (cerebral malaria, CM) that induced by Plasmodium falciparum assessed 47 SNPs of IL-22 and IL-22RA2 in children from Mali and Nigeria and revealed the involvement of IL-22 SNPs in the pathogenesis of CM." (PMID 31749919, 2019). "We report here genetic evidence for the involvement of IL-22 in cerebral malaria in children." (PMID 28139719, 2017). "We suggest that IL-22, acting in synergy with IL-17A, may have a deleterious effect in cerebral malaria, through the direct or indirect promotion of BBB permeability and brain inflammation, whilst protecting infected individuals against blood-stage infections and fatal liver tissue damage." (PMID 28139719, 2017). "The high IFNγ production of different splenic lymphocyte subsets at an early time point of PbA infection and the enhanced susceptibility for cerebral malaria symptoms in the absence of IL-22 might be due to an enhanced TH1 response during PbA infection." (PMID 27311945, 2016). "Interestingly, the lack of IL-22 led to an earlier occurrence of cerebral malaria (CM)." (PMID 27311945, 2016).
chronic hepatitis (6 papers, 2012 to 2018). An active inflammatory process affecting the liver for more than six months. "It is reported that in clinics and mouse model of chronic hepatitis and fibrosis, blockade of IL-22 attenuated hepatic expression of CXC10 and CCL20 and subsequently reduced Th17 recruitment and liver inflammation and fibrosis progression." (PMID 29383167, 2017). "Enhanced levels of systemic IL-22 have recently been observed in patients with chronic hepatitis and acute hepatitis B infection." (PMID 22967278, 2012). "In chronic hepatitis, IL-22-related pathology is dependent on the recruitment of Th17 cells." (PMID 27829708, 2016). "The limited data available suggest increased serum IL-22 in patients with acute HBV infection and in patients with chronic hepatitis, respectively." (PMID 22967278, 2012).
chronic hepatitis B virus infection (6 papers, 2012 to 2023). Chronic form of hepatitis B infection. "This study aimed to evaluate rs1179251 single nucleotide polymorphism in the IL-22 gene as a host factor and its effect on chronic hepatitis B infection." (PMID 31749919, 2019). "As known, Th17 cells secrete mainly IL-17 and IL-22 to perform their functions, contributing to the progression of chronic hepatitis B virus infection." (PMID 37875903, 2023). "So, in spite of the importance of IL-22 gene in immune responses, the studied polymorphism does not serve a decisive role in susceptibility to hepatitis B virus chronic infection." (PMID 31749919, 2019).
endothelial dysfunction (6 papers, 2016 to 2024). In vascular diseases, endothelial dysfunction is a systemic pathological state of the endothelium (the inner lining of blood vessels) and can be broadly defined as an imbalance between vasodilating and vasoconstricting substances produced by (or acting on) the endothelium. "It has also been shown that IL-22 can promote the growth of smooth muscle cells and endothelial dysfunction and remodeling, which are known to be some of the pathophysiological changes that occur in the course of PH, irrespective of the etiology." (PMID 38612795, 2024). "Exogenous IL-22 treatment aggravated endothelial dysfunction and elevated blood pressure, whereas an IL-22-neutralizing antibody had an exactly opposite effect." (PMID 32148441, 2020). "Serum IL-22 levels were recently shown to be positively correlated with blood pressure, and in AngII-induced hypertensive mice, evidence was found that IL-22 contributes to systemic and local inflammation, endothelial dysfunction, and increased blood pressure." (PMID 30619368, 2018). "Another mechanism that could explain the endothelial dysfunction induced by PM2.5 exposure, is the interleukin 22/interleukin 22 receptor (IL22/IL-22R) pathway." (PMID 36875486, 2023).
Guillain-Barre syndrome (6 papers, 2012 to 2024). A spectrum of rare post-infectious neuropathies that usually occur in otherwise healthy patients. "Recently, increased plasma and CSF levels of IL-22 have been reported for subjects diagnosed with Guillain-Barré syndrome, another acute autoimmune-mediated inflammatory demyelinating disease." (PMID 26295034, 2015).
infectious colitis (6 papers, 2015 to 2025). A viral or bacterial infectious process affecting the large intestine. "IL-22 is important in the clearance of the mouse pathogen C. rodentium, which causes infectious colitis that mimics E. coli infection in humans." (PMID 26793707, 2015). "Accordingly, most of the IL-22-producing CD4 T cells of lamina propria co-express T-bet during infectious colitis." (PMID 28408906, 2017). "The conundrum was addressed in our study, which reported that IL-6, not IL-23, is the critical cytokine required for optimal differentiation of host-protective IL-22-producing Th22 subsets during Citrobacter rodentium-induced infectious colitis." (PMID 28408906, 2017). "In a mouse model of infectious colitis, Lee and colleagues found the CD11b+ Ly6C+ Ly6G+ subset of neutrophils were the main source of IL-22 secretion." (PMID 26793707, 2015). "Zheng and colleagues investigated the role of IL-22 in protecting colonic tissue from infectious colitis with C. rodentium, paralleling infection by enterohemorrhagic E. coli (EHEC), and enteropathogenic E. coli (EPEC) in humans." (PMID 26793707, 2015). "Cells that express IL1-R1 are an important source of IL-22, which is in turn required for the coordination of effective responses against Salmonella owing to its ability to drive protective cytokine production and to prevent infectious colitis." (PMID 34222406, 2021). "It is likely that IL-22-expressing Th17 cells are a distinct population compared to IL-22 expressing Th22 cells as inhibition of TGFβ signaling during infectious colitis specifically depletes IL-22-producing Th17 cells but increases the frequency of IL-22-producing Th22 cells." (PMID 28408906, 2017). "Moreover, a recent study has demonstrated that activation of signal transducer and activator of transcription factor 3 (STAT3) was required for IL-22 production by Th22 cells and was responsible for effective host clearance of infectious colitis." (PMID 26793707, 2015). "Furthermore, infectious colitis with C. rodentium can be suppressed with ILC production of IL-22 in an AhR and microbiota-dependent manner." (PMID 26793707, 2015).
interstitial lung disease (6 papers, 2011 to 2023). A diverse group of lung diseases that affect the lung parenchyma. "Finally, SSc interstitial lung disease (ILD) was strongly associated with higher numbers of IL-22 and, to a lesser extent, IL-17A-producing cells." (PMID 21996293, 2011). "The results indicate an SSc-specific increase in the number of Th cells producing IL-22 and IL-17A, skewed to preferential homing into the lung and associated with interstitial lung disease (ILD)." (PMID 21996293, 2011). "Elevated levels of IL-22 were found in patients with T-cell-mediated lung diseases, such as interstitial lung disease." (PMID 35163689, 2022). "IL22 is essential for repairing lung tissue and maintaining epithelial cell homeostasis after an influenza virus infection, suggesting its promising role as an immunotherapy agent for interstitial lung disease." (PMID 37189778, 2023).
liver cancer (6 papers, 2014 to 2025). An epithelial or non-epithelial malignant neoplasm that arises from the liver. "Thus, this study aimed to investigate the role and underlying mechanisms of IL-22 and IL-22BP signaling in liver cancer." (PMID 36551508, 2022). "Elevated levels of IL-22 are relevant to a good amount of tumors, such as gastric, lung, pancreatic, colon, and liver cancers." (PMID 31750252, 2019). "Additionally, the cytokine IL‐22 has a dual function in balancing epithelial repair and tumor growth, making it a potential therapeutic target for liver cancer." (PMID 40236776, 2025). "However, in viral hepatitis, IL-22 is considered a pro-inflammatory cytokine and is thought to be involved in the development of liver cancer." (PMID 36611816, 2022). "Furthermore, we are the first ones to show a significant role of endogenous IL-22BP in controlling IL-22 in liver cancer." (PMID 36551508, 2022). "First, although IL-22 itself does not initiate liver tumor development, IL-22 is able to promote existing liver cancer cell proliferation and survival." (PMID 24623532, 2014). "IL-22 serum levels may reflect increased aggressiveness of liver cancer disease and act as a negative prognostic indicator in patients with HCC." (PMID 32760208, 2020).
Myocardial fibrosis (6 papers, 2014 to 2023). "Up-regulation of MMP9, MMP9/TIMP-1 ratio and down-regulation of TIMP-1 were more significant after neutralizing IL-22, associated with myocardial fibrosis exacerbation." (PMID 25547181, 2014). "Some studies also indicated that inflammation-related effector cytokines, such as IL-17 family members and IL-22 are associated with Th17 cells, and these effector cytokines were demonstrated to regulate the MMP/TIMP system to influence myocardial fibrosis." (PMID 36304554, 2022). "Treatment of mice with IL-22-specific antibody decreased the survival rate of the animals and exacerbated myocardial fibrosis suggesting the cardioprotective role of IL-22 through the inhibition of myocardial fibrosis." (PMID 26199463, 2015). "On week 2, 12 and 24 post initial injection, the percentage of splenic Th22 cells, the levels of plasma IL-22, cardiac IL-22 receptor (IL-22R) expression, and indicators of myocardial fibrosis were measured." (PMID 25547181, 2014). "The collagen volume fraction (CVF), the percentage of splenic Th22 cells, plasma IL-22 levels, cardiac IL-22R expression and indicators of myocardial fibrosis were then monitored." (PMID 25547181, 2014). "Treatment of AVMC and chronic myocarditis mice with an anti-IL-22 Ab decreased the survival rate and exacerbated myocardial fibrosis." (PMID 25547181, 2014). "Neutralization of IL-22 exacerbated myocardial fibrosis with down-regulation of the percentage of splenic Th22 cells, circulating IL-22 and myocardial IL-22R expression." (PMID 25547181, 2014). "IL-22 is a myocardium-protective cytokine by inhibiting myocardial fibrosis." (PMID 25547181, 2014). "Then the myocardial fibrosis increased and survival rate decreased in mice after neutralizing IL-22, accompanied by a decline in Th22 cell number, reduced IL-22, diminished IL-22R expression and increased indicators of myocardial fibrosis such as COL1-A1, COL3-A1, MMP9." (PMID 25547181, 2014). "Moreover, the severity of myocardial fibrosis in chronic myocarditis after neutralizing IL-22 is similar to DCM." (PMID 25547181, 2014). "Thus, Th22 cells and IL-22 play a protective role in DCM by inhibiting myocardial fibrosis and act as therapeutic targets." (PMID 25547181, 2014). "We further explored the effect of neutralizing anti-IL-22 antibody (Ab) on myocardial fibrosis." (PMID 25547181, 2014). "While a neutralizing antibody against IL-22 led to increased COL1-A1, COL3-A1, MMP9 expression, and intensified myocardial fibrosis in DCM mice, suggesting that IL-22 protects the myocardium by inhibiting myocardial fibrosis." (PMID 36827455, 2023). "In summary, our study demonstrated that the up-regulations of IL-22-producing Th22 cells may play an important part in the pathogenesis of CVB3-induced mice chronic myocarditis and DCM by inhibiting myocardial fibrosis." (PMID 25547181, 2014).
myocarditis (6 papers, 2012 to 2025). Myocarditis is a condition that is characterized by inflammation of the heart muscle (myocardium). "Eosinophil-derived IL-4 is important for chronic disease progression in myocarditis, and IL-22BP blocks protective functions of IL-22 in UC." (PMID 28496445, 2017). "The expression levels of IL-21 and IL-22 are markedly increased in acute virus-induced myocarditis (AVMC), and IL-22 exacerbates the severity of AVMC20." (PMID 27198976, 2016). "And the promotion of IL-22R1 further aggravates the myocarditis in the anti-IL-22 group." (PMID 23050732, 2012). "For instance, considering that opioid use exacerbates the up regulation of IL-6, it may worsen the inflammation and consequent cardiovascular outcomes (e.g., myocarditis, plaque rupture) related to the cytokine storm of L-6, IL-7, and IL-22 induced by the viral invasion of SARS-CoV-2." (PMID 34803676, 2021).